RN7SKP3 (RN7SK pseudogene 3)
Gene: Miscellaneous RNA gene on chromosome 13 (45,060,729 to 45,061,086, forward strand). Ensembl gene ENSG00000223341.
Homologues: Orthologues: chimpanzee 7SK (99% identical), mouse Gm55378 (50% identical). Paralogues in human: RN7SKP79 (69% identical), 7SK (67% identical), RN7SKP180 (67% identical), RN7SKP255 (65% identical), RN7SKP214 (65% identical), RN7SKP6 (65% identical), RN7SKP103 (64% identical), RN7SKP133 (64% identical), RN7SKP250 (64% identical), RN7SKP48 (64% identical), RN7SKP71 (64% identical), RN7SKP185 (64% identical), and 284 more.